PAN2 (poly(A) specific ribonuclease subunit PAN2)
Description:
Catalytic subunit of the poly(A)-nuclease (PAN) deadenylation complex, one of two cytoplasmic mRNA deadenylases involved in general and miRNA-mediated mRNA turnover. PAN specifically shortens poly(A) tails of RNA and the activity is stimulated by poly(A)-binding protein (PABP). PAN deadenylation is followed by rapid degradation of the shortened mRNA tails by the CCR4-NOT complex. Deadenylated mRNAs are then degraded by two alternative mechanisms, namely exosome-mediated 3'-5' exonucleolytic degradation, or deadenylation-dependent mRNA decaping and subsequent 5'-3' exonucleolytic degradation by XRN1. Also acts as an important regulator of the HIF1A-mediated hypoxic response. Required for HIF1A mRNA stability independent of poly(A) tail length regulation.
Synonyms: KIAA0710; USP52; hPAN2; DEDCRF
Tractability: PROTAC: ubiquitination databases record sites on it; its protein half-life has been measured.
Gene: Protein-coding gene on chromosome 12 (56,316,223 to 56,334,053, reverse strand). Ensembl gene ENSG00000135473.
Subcellular location: Cytoplasm; Cytoplasm, P-body; Nucleus
Pathways (Reactome):
Metabolism of RNA: Deadenylation of mRNA
Gene Ontology:
Molecular function: 3'-5'-RNA exonuclease activity; poly(A)-specific ribonuclease activity; protein binding; cysteine-type deubiquitinase activity; nucleic acid binding
Biological process: nuclear-transcribed mRNA poly(A) tail shortening; nuclear-transcribed mRNA catabolic process, deadenylation-dependent decay; positive regulation of cytoplasmic mRNA processing body assembly
Cellular component: cytoplasm; nucleus; PAN complex; cytosol; P-body
Genetic constraint (gnomAD): Loss-of-function variants: 65 observed, 134.5 expected, observed/expected ratio (o/e) 0.48, 90% interval 0.4 to 0.59. The synonymous counts are far from expectation, so gnomAD's model fits this gene poorly and the ratio says little. Missense variants: 1,010 observed, 1,529 expected, observed/expected ratio (o/e) 0.66, 90% interval 0.63 to 0.7. Synonymous variants: 452 observed, 558.73 expected, observed/expected ratio (o/e) 0.81, 90% interval 0.75 to 0.87.
Gene-disease validity (ClinGen):
ClinGen rates the evidence that PAN2 causes each of these diseases.
syndromic complex neurodevelopmental disorder (autosomal recessive): Moderate. A disorder that involves more than one phenotype associated with the central nervous system, including but not limited to intellectual disability, autism, and seizures (epilepsy), and also a distinctive pattern of other features including dysmorphisms and/or congenital malformations.
Homologues: Orthologues: chimpanzee PAN2 (99% identical), pig PAN2 (98% identical), dog PAN2 (98% identical), rabbit PAN2 (97% identical), guinea pig PAN2 (97% identical), mouse Pan2 (96% identical), rat Pan2 (96% identical), macaque PAN2 (88% identical), tropical clawed frog pan2 (80% identical), zebrafish pan2 (75% identical), Drosophila melanogaster PAN2 (43% identical), Caenorhabditis elegans panl-2 (27% identical).
Diseases named in the same sentence as PAN2 in open-access papers:
PAN2 is named in the same sentence as 27 diseases in open-access papers, as found by Europe PMC text mining. Sharing a sentence is not in itself a finding about the gene and the disease. The quoted sentences say what the papers report.
bladder cancer (3 papers, 2024 to 2025). "An siRNA screen targeting 96 deubiquitinases identifies USP52/PAN2 as crucial for xCT stability and ferroptosis in bladder cancer (BLCA)." (PMID 39392373, 2024).
influenza infection (1 paper, 2022). "We endogenously deleted two CREs containing expression-modulation variants linked to immune function, rs11624425 and rs80317430, identifying their primary genic targets as ELMSAN1, and PAN2 and STAT2, respectively, three genes differentially expressed during influenza infection." (PMID 34662402, 2022).
infection (2 papers, 2017 to 2026). The state of being infected such as from the introduction of a foreign agent such as serum, vaccine, antigenic substance or organism. "Here, we uncover that the Pan2-Pan3 deadenylase complex is a master regulator of infection in the rice blast fungus Magnaporthe oryzae." (PMID 41556236, 2026). "Six UPS factors were discovered to be essential for infection with the three viruses (DCAF12L, DDB1, FBXL19, OTUD6A, PAN2, and PHC2)." (PMID 29202037, 2017).
autosomal recessive disease (1 paper, 2023). Autosomal recessive form of disease. "With our study, we provided Moderate or Strong level of evidence for GDR for 11 genes that were not listed in OMIM as having phenotype entity: FBRSL1, AGR2, ACBD6, C1orf127, PAN2, VPS50, KCTD3, NOTCH3 (for autosomal recessive disease), FAT1, NRAP, and SCLT1." (PMID 39669245, 2023).
PAN2 also shares sentences with these, for which no sentence is quoted: tumor (8 papers); cancer (7); breast carcinoma (3); colorectal cancer (3); lung carcinoma (2); osteosarcoma (2); bone cancer (1); breast (1); breast tumor (1); colon adenocarcinoma (1); colon cancer (1); gastric cancer (1); glioblastoma (1); hearing loss (1); Insulin resistance (1); myeloma (1); neuroblastoma (1); neurological diseases (1); non-small cell lung carcinoma (1); pancreatic cancer (1); rectum (1); renal carcinoma (1); retinal degeneration (1).